IL6 (interleukin 6)
Diseases named in the same sentence as IL6 in open-access papers (continued):
Sharing a sentence is not in itself a finding about the gene and the disease.
Thrombocytopenia (160 papers, 2008 to 2026). A reduction in the number of circulating thrombocytes. "Our data also demonstrate that thrombocytopenia is associated with an increase in IL-1, IL-6, IL-8, IL-10, and TNF-α." (PMID 34585667, 2021). "The pathophysiological process causes thrombocytopenia and elevation of IL-6, a key proinflammatory cytokine in thromboinflammatory processes." (PMID 33425951, 2020). "In another study, thrombocytopaenia in patients with P. vivax infection was associated with increased IL-1, IL-6, IL-10, and TGF-β." (PMID 30126413, 2018). "In a recent study, thrombocytopenia was associated to elevated levels of IL-27, IL-10 and IL-6 cytokines." (PMID 28231825, 2017). "Activity of the VWF-cleaving-protease, ADAMTS13, was deficient in proportion to endothelial activation, IL-6, thrombocytopenia and vivax disease-severity, and associated with impaired microvascular reactivity in severe disease." (PMID 25569250, 2015). "Increased expression of IL-6 is associated with clinically severe Nephropathia epidemica (NE), and high IL-6 was found to be an independent risk factor for impaired renal function, thrombocytopenia, and longer hospitalization." (PMID 24714064, 2014). "We found that maximum plasma IL-6 was associated with the severity of renal insufficiency, blood leukocytosis and thrombocytopenia." (PMID 20500875, 2010). "High IL-6 was found to be an independent risk factor for impaired renal function, thrombocytopenia, and longer hospitalization, when examined together with high CRP and age." (PMID 20500875, 2010). "Logistic regression analyses were then carried out to evaluate the associations of high CRP and high IL-6 with high serum creatinine, thrombocytopenia, or hospitalization exceeding seven days." (PMID 20500875, 2010). "The mechanisms underlying thrombocytopenia may be related to increased levels of circulating cytokines, particularly interleukin-6 (IL-6)." (PMID 40458756, 2025). "The immune dysregulation in ITP not only causes thrombocytopenia but also triggers a persistent low-grade systemic inflammatory response through the activation of pro-inflammatory cytokine networks, such as interleukin-6 (IL-6) and tumor necrosis factor-α (TNF-α)." (PMID 41211279, 2025). "However, treatments with tocilizumab or other monoclonal antibodies against IL-6 are associated with adverse effects such as gastrointestinal haemorrhage, thrombocytopenia, and neutropenia." (PMID 38600086, 2024). "Leukopenia, thrombocytopenia, erythrocytopenia, and bone marrow cell depletion are caused by radiation therapy associated with hemorrhage, which increases the production of IL-1, IL-6, and IL-17A in the IL-17 signaling pathway and increases BMS." (PMID 37654610, 2023). "It is reported that TAFRO syndrome patients were often associated with an elevated VEGF level and a lower IL-6 level, with a normal level of immunoglobulin (Ig), also characteristic with small lymph nodes, obvious thrombocytopenia, pleural effusion and ascites." (PMID 31938902, 2020). "Finally, we observed that IL-6, a cytokine known to be inflammatory and already associated with a more severe prognosis in the evolution of VL, was correlated to laboratory severity markers, such as hypoalbuminemia, leukopenia and thrombocytopenia." (PMID 33874901, 2021). "Here, we showed for the first time, that oncolytic tumor therapy could be optimized through reduction of therapeutic side effects associated with chemotherapy such as thrombocytopenia, in mice receiving combination therapy with mitomycin C by using a hyper-IL-6-encoding vaccinia virus." (PMID 22236378, 2012). "High plasma IL-6 was also found to be an independent risk factor for thrombocytopenia and hospitalization exceeding seven days (OR 3.6, 95% CI 1.6-8.0, P = 0.002, and OR 4.5, 95% CI 1.9-10.8, P < 0.001, respectively) in models including high plasma IL-6, high plasma CRP, and age." (PMID 20500875, 2010).
Thrombocytopenia (continued). "In contrast, anti-IFN-γ treatment alone significantly improves hepatosplenomegaly, while single treatment with anti-IFNAR only improves thrombocytopenia and minimizes the expression of inflammatory cytokines (Il6, Il12b, and Tnfa)." (PMID 41561071, 2026). "We also observed a distinct cytokine profile in patients with thrombocytopenia (MT group), characterized by elevated IL-6, IFN-γ, and IL-10 levels, along with reduced TGF-β1." (PMID 40690473, 2025). "The laboratory features of cytokine storms include haematological anomalies, such as leucocytosis or leukopenia, thrombocytopenia, and disseminated intravascular coagulation; high fibrinogen levels; elevated IL-6; and general markers of end-organ dysfunction." (PMID 38255162, 2023). "We also observed thrombocytopenia and elevated D-dimer and IL-6 levels among RT-PCR-positive patients." (PMID 36532907, 2022). "Thrombocytopenia (2.42 vs 1.76; P = 0.009), D-dimer levels (408.91 vs 123.06; P = 0.03), and interleukin (IL-6) levels (219.3 vs 80.81; P = 0.04) were significantly elevated among RT-PCR positive patients." (PMID 36532907, 2022). "The mTOR inhibitor sirolimus, which preferentially inhibits mTORC1, has led to sustained remission in a small cohort of anti‐IL‐6‐refractory iMCD patients with thrombocytopenia, anasarca, fever, renal dysfunction and organomegaly (iMCD‐TAFRO)." (PMID 35488725, 2022). "IL6 has been proven to be a potent stimulator in the maturation of megakaryocytic lineages in vitro and in vivo, which can effectually prevent thrombocytopenia." (PMID 36297316, 2022). "IL-2, TNF-α, VEGF-D, and IL-6 were correlated with thrombocytopenia and these markers were valuable for predicting bleeding." (PMID 35631079, 2022). "Thrombocytopenia elevated D-dimer, and IL-6 were found among RT-PCR patients, whereas CRP, NLR, and ferritin were found among RT-PCR-negative patients." (PMID 36532907, 2022). "Patients with severe thrombocytopenia had the highest IL-6 concentrations, compared to patients with moderate/mild thrombocytopenia." (PMID 36178979, 2022). "Megakaryocytes usually produce more platelets when IL-6 is boosted, which contradicts the occurrence of thrombocytopenia." (PMID 35655778, 2022). "This suggests that tocilizumab would inhibit the IL-6-induced thrombopoietin expression and thus results in thrombocytopenia." (PMID 36091800, 2022). "We can only indirectly measure inflammation and hypercoagulability through elevated blood markers for inflammation (like CRP, interleukin 6, ferritin) along with elevated D-Dimers, prolonged prothrombin time, and thrombocytopenia." (PMID 33619668, 2021). "On the other side, biological behavior plays the decisive role in prognosis of advanced-stage HCC, HCC patients with thrombocytopenia which reflected less thrombopoietin and IL-6 induced by less malignant tumor would have a better prognosis." (PMID 33573630, 2021). "Low levels of sRAGE were associated with increased levels of IL-6, VCAM-1 and PAI-1 as well as with thrombocytopenia." (PMID 31635193, 2019). "IL-6, IL-10 and TNF production has been associated with thrombocytopenia in P. vivax malaria patients." (PMID 30199554, 2018). "A subset of cytokines consisting of IL-1β, IL-8, IL-6, TNF-α, and IL-10 was also coordinately high and significantly associated with severity of thrombocytopenia in HA patients." (PMID 28628633, 2017). "Recombinant human IL-6 significantly improved recovery from chemotherapy-induced thrombocytopenia in clinical trials." (PMID 26367124, 2015). "Insignificant increase in IL-6 levels (p value = 0.352) was observed in uncomplicated and complicated cases exhibiting profound thrombocytopaenia." (PMID 25128199, 2014). "Several host factors including cell-mediated immune cells, such as IL-1, IL-6 and IL-10 have been documented for P. vivax-induced thrombocytopaenia." (PMID 25128199, 2014).
Thrombocytopenia (continued). "This subject developed grade 3 liver toxicity, marked increase in interleukin-6 (IL-6), thrombocytopenia, and laboratory signs of disseminated intravascular coagulopathy." (PMID 24883229, 2013). "Phase I and II clinical trials utilizing recombinant human IL-6 in conjunction with chemotherapy increased OC patient platelet count alleviating thrombocytopenia, thereby comprising adjuvant therapeutic benefits of IL-6." (PMID 21765834, 2011). "A major group of genes (GMCSF, RANTES, IL2, INFγ, TLR6, CCR2A, IL-6, CKR-4) causing thrombocytopenia and vascular permeability was also found to be up-regulated in all three cell types." (PMID 19117515, 2008). "For instance, elevated levels of HBP and CRP in conjunction with increased TNF-α and IL-6 can serve as early indicators of severe disease, while thrombocytopenia may signal impending complications such as DIC." (PMID 40963970, 2025). "Regarding thrombocytopenia, IL-6 inhibitors should be used with caution." (PMID 38979406, 2024). "The elevation of platelet and coagulation-related factors such as PF4 (CXCL4), also regulated by IL-6, may be related to the increased incidence of thrombocytopenia among PWID." (PMID 38920641, 2024). "Spleen volume and PAIgG have been suggested to be involved in CLD thrombocytopenia, but in the present study, it is unclear whether IL-6 also plays a role." (PMID 36221332, 2022). "These organ failures may be associated with clinical and laboratory signs of inflammation, including fever, thrombocytopenia, hyperferritinemia, and elevations of C-reactive protein and interleukin-6 (IL-6)." (PMID 36009884, 2022). "Especially for IL-6, the patients with thrombocytopenia had persistently elevated levels at 1–10 days, 11–20 days and 21–30 days after symptom onset, with their difference from the non-thrombocytopenia group further enlarged, which were significant at 1–10 days and 11–20 days after symptom onset." (PMID 35791362, 2022). "As for thrombocytopenia, studies revealed that IL-1β together with IL-6 and IL-8, could increase hypercoagulability of whole blood and induce platelet hyper-activation and spreading." (PMID 33767707, 2021). "Second, to determine whether platelets are involved in the physiological elevation of IL-6 necessary for the onset of liver regeneration in vivo, severe thrombocytopenia was induced in mice using a platelet-depleting antibody." (PMID 32443494, 2020). "A combination of LPS and IL-6 resulted in higher levels of platelet recovery after the 5-FU-induced thrombocytopenia, indicating that their additive effects are greater than those observed in platelet recovery in thrombocytopenic mice compared with normal mice." (PMID 26330186, 2015). "Thus, a finding of non-significant increase in IL-6 levels in mild, moderate and profound thrombocytopaenic cases implies that regulation of platelet production by IL-6 is disturbed in P. vivax cases leading to worsening thrombocytopaenia status." (PMID 25128199, 2014). "Although this has previously been shown to have remarkable success in preclinical tumor models, the virus-mediated expression of the designer cytokine hyper-IL-6 offered a new approach to significantly reduce the duration of thrombocytopenia, a serious side effect of chemotherapy." (PMID 22236378, 2012). "Moreover, hyper-IL-6 expression greatly reduced the time interval during which the mice suffered from chemotherapy-induced thrombocytopenia." (PMID 22236378, 2012). "Therefore, more clinical trials should be completed to test the efficiency of IL-1 and/or IL-6 to ameliorate thrombocytopenia." (PMID 21765834, 2011). "In RCC patients, thrombocytopenia is mainly attributed to paraneoplastic syndromes, such as secondary ITP (approximately 20% of all RCC patients), followed by other causes, including IL-6-related thrombocytopenia, secondary DIC, and a few unknown causes." (PMID 39845199, 2024).
Thrombocytopenia (continued). "The patient had many risk factors that could leed to CRS and/or NT, including high disease burden, severe thrombocytopenia, hyperpyrexia (38.5–41.0°C), blood platelet levels less than 60, and IL-6 higher than 16 pg/mLin the first 36 h after the CD19 CAR T-cell infusion." (PMID 33604290, 2020). "Here, the hyper-IL-6-encoding rVACV strain GLV-1h90 was used to reduce the side effects resulting from the chemotherapeutic agent mitomycin C. This chemotherapeutic agent, as well as most other agents, is known to cause severe thrombocytopenia in mice as well as in human patients." (PMID 22236378, 2012). "Clinically recombinant IL-1 and IL-6 may alleviate chemotherapy-induced thrombocytopenia." (PMID 21765834, 2011). "Mechanistically, thrombocytopenia impaired 5-HT uptake and reduced nocturnal melatonin secretion, while elevated hs-CRP and IL-6 indicated inflammation-driven hypothalamic-pituitary-adrenal axis dysregulation." (PMID 41211279, 2025). "Our findings reveal significantly elevated sCP levels in SFTS patients, positively correlated with viral load, thrombocytopenia severity, and multiple pro-inflammatory cytokines (TNF-α, IL-6, IL-8, IL-10)." (PMID 40657502, 2025). "In conclusion, our study suggests that thrombocytopenia in P. vivax infection may be driven by a combination of immune responses, including autoantibody-mediated recognition of phosphatidylserine on activated platelets and a proinflammatory cytokine dominated by IL-6 and IFN-γ." (PMID 40690473, 2025). "SFTSV infection triggers a cytokine storm (e.g., elevated IL-6, IL-10, TNF-α), resulting in direct vascular endothelial damage and increased permeability, which contribute to thrombocytopenia and multiorgan dysfunction." (PMID 40794812, 2025). "At 3 months of age, the infant developed septic shock, with thrombocytopenia and elevated inflammatory markers (C-reactive protein (CRP) 148 mg/L, procalcitonin (PCT) >100 ng/mL, interleukin-6 (IL-6) 20,000 pg/mL)." (PMID 40723093, 2025). "Both the conditions result in the hype of inflammatory cytokines including interleukin-6 (IL-6) and tumor necrosis factor-α (TNF-α) thrombocytopenia, vascular microthrombosis and multi-organ dysfunction." (PMID 39678231, 2024). "In this study, the fluctuations in TPO, IL-6, and PAIgG levels before and after PSE for thrombocytopenia were investigated in patients with liver cirrhosis and hypersplenism." (PMID 36221332, 2022). "When attempting to improve thrombocytopenia with PSE, adequate splenic embolization needs to be obtained together with improvements in IL-6, PAIgG, and TPO levels." (PMID 36221332, 2022). "We identified significant correlations between serum IL-2, IL-6, TNF-α, and VEGF-D levels and thrombocytopenia in DENV-infected patients in the present study, consistent with the findings of other reports." (PMID 35631079, 2022). "Other abnormal laboratory findings included thrombocytopenia, elevated erythrocyte sedimentation rate (ESR), lactate dehydrogenase (LDH), D-dimer, troponin and cytokine levels, particularly interleukin 6 (IL-6)." (PMID 34003850, 2021). "The incidences of reduced lymphocytes, thrombocytopenia, hypoalbuminemia, elevated C-reactive protein, ferritin, LDH, interleukin-6, PCT, and FIB were 61.51%, 26.42%, 77.92%, 98.5%, 86.79%, 80.59%, 89.30%, 85.10%, and 87.01%, respectively." (PMID 34336288, 2021). "ROC curves and AUC values for IL-6, PCT and CRP were calculated with respect to predicting inotropic support need, intubation and thrombocytopenia within 3 days of suspicion." (PMID 33407770, 2021). "A general increase in IL-6 was recorded in overall TAVI recipients, but a high serum level of IL-8, a potent thrombocytopenia inducer, was measured in Portico recipients only, including those with extra-rinsed valve." (PMID 33721196, 2021). "At that point in time, IL-6 and D-dimer concentrations peaked at 3.300 ng/l and 19 μg/ml FEU respectively, whereas thrombocytopenia worsened despite anticoagulation." (PMID 32607684, 2020).
Thrombocytopenia (continued). "PLAG significantly decreased plasma levels of the chemokine (C–X–C motif) ligand 1 (CXCL1), CXCL2, interleukin (IL)-6, and C-reactive protein (CRP), which were elevated consistently with the occurrence time of neutropenia, monocytopenia, and thrombocytopenia." (PMID 31752148, 2019). "In this study, the samples were analyzed for the prevalence and assessment of degree of thrombocytopenia, as well as for cytokines such as TNF-α, IL-6, and IL-10." (PMID 31110658, 2019). "Association of cell-mediated immune cells, such as interlukin-1 (IL-1), IL-6, IL-10, tumour necrosis factor (TNF) and transforming growth factor-β (TGF-β) and thrombocytopaenia have been documented in various studies." (PMID 25128199, 2014). "A retrospective analysis of clinical data from 290 SFTS patients from the First and Second Affiliated Hospitals of Anhui Medical University confirmed previously reported abnormalities including lymphocytopenia, thrombocytopenia, elevated levels of AST, ALT, LDH, and cytokines (IL‐6, IL‐1β, TNF‐α)." (PMID 41090515, 2026). "This was further supported by a dysregulated cytokine profile, characterized by elevated levels of IFN-γ, IL-6, and IL-10 in patients with thrombocytopenia compared to those without." (PMID 40690473, 2025). "Thrombocytopenia is also common, along with increased levels of D-dimer and inflammatory markers such as C-reactive protein (CRP), erythrocyte sedimentation rate (ESR), interleukin-6 (IL-6), and procalcitonin." (PMID 39599799, 2024). "The various stages of infection are characterized by high levels of inflammatory markers such as CRP, interleukins (IL-2, IL-6, IL-7), LDH, ferritin, lymphocytopenia, thrombocytopenia, leukopenia, elevated procalcitonin, D-dimer, prothrombin, fibrinogen, and others." (PMID 36982882, 2023). "Additionally, EIII-SNPs induce exacerbated thrombocytopenia, worsen hemorrhage pathogenesis, and the induction of pro-inflammatory cytokines TNF-α, IL-1β, IL-6, and anti-inflammatory cytokine IL-10 in mice." (PMID 37298220, 2023). "Therefore, fluctuations in PAIgG, IL-6, and TPO with PSE for thrombocytopenia in patients with chronic liver disease due to hypersplenism were investigated." (PMID 36221332, 2022). "Thrombocytopenia and hepatic enzyme elevations that can be observed with IL-6 inhibitors were not seen in our small patient population (n = 10)." (PMID 35497778, 2022). "Severe thrombocytopenia was positively correlated with IL-4, CXCL10, IL-6, IL-10 and IFN-γ levels, renal dysfunction was related to an increase in IL-2, IL-1β, IL-17A and IL-8, and hepatic impairment with CXCL10, MCP-1, IL-6 and IFN-γ." (PMID 36178979, 2022). "Elevated levels of inflammation markers, including interleukin 6 (IL-6), tumor necrosis factor α (TNF-α), C-reactive protein (CRP) and procalcitonin, were observed at 1–10 days or 11–20 days after symptom onset in the patients with thrombocytopenia." (PMID 35791362, 2022). "Thrombocytopenia and hypoglycemia were the most characteristic manifestations in the severe P. vivax malaria group, having a shared pro-inflammatory cytokine/chemokine profile (IFN-γ, IL4, IL6 and CXCL10)." (PMID 36178979, 2022). "IL-6 production in the absence of TLR stimulation negatively correlated with thrombocytopenia, but only in patients with higher a-SOFA scores." (PMID 33690725, 2021). "Irrespective of infecting species, the IL-6/IL-10 ratio also showed a significant decrease with an increase in thrombocytopenic intensity, especially during severe thrombocytopenia." (PMID 31110658, 2019). "We speculate that biomass-related IL-6 may contribute to impaired ADAMTS13 activity and accumulation of UL-VWF multimers, and may thereby contribute to microvascular dysfunction, thrombocytopenia and disease severity in vivax malaria." (PMID 25569250, 2015). "IL-6 was also associated with presence of pleural effusion/ascites in DHF, consistent with an earlier report but not with thrombocytopenia or increased ALT." (PMID 20090849, 2010).